SPTBN1 (spectrin beta, non-erythrocytic 1)
Diseases named in the same sentence as SPTBN1 in open-access papers (continued):
Sharing a sentence is not in itself a finding about the gene and the disease.
pancreatic cancer (6 papers, 2020 to 2023). "Reduced SPTBN1 levels were discovered in colon and pancreatic cancer, potentially contributing to tumor initiation or progression." (PMID 34390367, 2021). "It has also been reported that SPTBN1 plays an important role in the pathogenesis and progression of many tumors, such as liver cancer, lung cancer, pancreatic cancer and colon cancer." (PMID 32516133, 2020). "Indeed, in a proteomics study of 55 pancreatic cancer patients, lower levels of SPTBN1 correlate with advanced PDAC stage and worse prognosis, and similar data were reported in a cohort of 82 resected PDAC patients." (PMID 33383671, 2020).
autism (4 papers, 2023 to 2025). Persistent deficits in social interaction and communication and interaction as well as a markedly restricted repertoire of activity and interest as well as repetitive patterns of behavior. "Previous studies found that mutations in the Sptbn1 SRs may lead to developmental delay, autism and intellectual disability, which means that the SRs are crucial to the function of Sptbn1." (PMID 37284462, 2023). "Genes reported as potential blood biomarkers of mental health, such as PACSIN1 and SPTBN1 (associated with addiction-related behavior), GPR19 (associated with depression), and AUTS2 (associated with autism), were highlighted in the STRING analysis of this study." (PMID 40917096, 2025).
developmental delay (4 papers, 2022 to 2025). "For example in the case of three patients carrying the same Arg1003Trp mutation of SPTBN1 (βII spectrin), only one suffers from seizures and only one has an abnormal brain MRI, while all of them share developmental delay features." (PMID 36831804, 2023). "Spectrin Beta, Non-Erythrocytic 1 (SPTBN1) has previously been implied in neural development and function, particularly cortical organization, developmental delay and behavioral deficits." (PMID 40281224, 2025).
Intellectual disability (4 papers, 2020 to 2026). "Missense and pLoF variants in SPTBN1 cause a neurodevelopmental disorder characterized by intellectual disability, language and motor delays, autistic features and seizures." (PMID 40836029, 2026). "SPTBN1 was recently implicated in a neurodevelopmental disorder characterized by intellectual disability, language and motor delays, autistic features, and seizures (MIM: 619475)." (PMID 40225914, 2024).
lung carcinoma (4 papers, 2012 to 2023). "Accordingly, increased SPTBN1 expression (and over-representation of aTOH1/cTOH3 in controls over cases) could plausibly protect against lung cancer by increasing immune surveillance, given that we know that smoking suppresses the CD4/CD8 T cell ratio." (PMID 22384118, 2012).
ovarian carcinoma (4 papers, 2020 to 2023). A malignant neoplasm originating from the surface ovarian epithelium. "Our data indicated that SPTBN1 inhibited cell viability and migration in epithelial ovarian cancer by inhibiting the JAK/STAT signaling pathway through regulation of SOCS3." (PMID 32516133, 2020). "SPTBN1 plays an anticancer role in many kinds of tumors and participates in the chemotherapeutic resistance of epithelial ovarian cancer (EOC)." (PMID 32516133, 2020). "In conclusion, our study demonstrated that suppression of SPTBN1 promoted cell growth and migration in epithelial ovarian cancer by activating JAK/STAT signaling pathways, which are blocked by SOCS3." (PMID 32516133, 2020). "In this study, we investigated the role of SPTBN1 in the development and metastasis of epithelial ovarian cancer and its molecular mechanisms." (PMID 32516133, 2020). "Using the EOC cell lines A2780 and HO8910, we verified that SPTBN1 inhibits the growth of epithelial ovarian cancer cells in vitro and in vivo and the migration of epithelial ovarian cancer cells in vitro." (PMID 32516133, 2020). "The results showed that the expression of SPTBN1 gradually decreased with the progression of ovarian cancer, and the PFS of patients with low SPTBN1 expression was shorter than that in patients with high SPTBN1 expression." (PMID 32516133, 2020). "Our results suggest that SPTBN1 suppresses the progression of epithelial ovarian cancer via SOCS3-mediated blockade of the JAK/STAT3 signaling pathway." (PMID 32516133, 2020). "In this study, we identified the relationship between SPTBN1 and the stage and prognosis of epithelial ovarian cancer by analyzing the TCGA database." (PMID 32516133, 2020). "Our work revealed that SPTBN1 suppresses the growth and metastasis of epithelial ovarian cancer via SOCS3-mediated blockade of the JAK/STAT3 signaling pathway." (PMID 32516133, 2020). "The data indicate that SPTBN1 may promote the malignant biological behaviors of epithelial ovarian cancer." (PMID 32516133, 2020). "Then, the expression of SPTBN1 in eight ovarian cancer cell lines was measured by western blotting." (PMID 32516133, 2020). "However, the effects of SPTBN1 on the growth and metastasis of epithelial ovarian cancer and the specific mechanism have rarely been reported and need to be further studied." (PMID 32516133, 2020). "However, the effects and mechanisms of SPTBN1 on the progression and metastasis of epithelial ovarian cancer are still unknown." (PMID 32516133, 2020). "PIK3R3 expression was lower in USP4, SPTBN1, and SORBS2-mutant ovarian cancer patients than in ovarian cancer patients with wild type genes." (PMID 35761259, 2022). "Thus, SPTBN1 may be a novel and useful candidate target for ovarian cancer treatment." (PMID 32516133, 2020). "It should be investigated whether SPTBN1-regulated SOCS3 is involved in inflammation and radioresistance during ovarian cancer progression in future studies." (PMID 32516133, 2020).
colorectal cancer (3 papers, 2018 to 2023). A primary or metastatic malignant neoplasm that affects the colon or rectum. "In particular, Tang and colleagues pointed out that SPTBN1/Smad4/TGF β signaling acts as a suppressor of colorectal cancer progression." (PMID 38069214, 2023). "The SPTBN1-ALK fusion gene was formed by the fusion of exon 7 of the SPTBN1 gene with exon 20 of the ALK gene, which was first identified in colorectal cancer." (PMID 30445769, 2018).
epilepsy (3 papers, 2012 to 2023). A brain disorder characterized by episodes of abnormally increased neuronal discharge resulting in transient episodes of sensory or motor neurological dysfunction, or psychic dysfunction. "Sptan1 mutation is associated with epilepsy, and Sptbn1 is implicated in ASDs." (PMID 33192291, 2020). "The OTUD7A protein–protein interaction network included synaptic, axonal, and cytoskeletal proteins and was enriched for ASD and epilepsy risk genes (Ank3, Ank2, SPTAN1, SPTBN1)." (PMID 36604605, 2023). "Alpha-actinin-4 (ACTN4) also belongs to the spectrin superfamily playing complementary roles to SPTBN1 and SPTBN2 and has been implicated in central nervous system (CNS) disorders such as schizophrenia and epilepsy." (PMID 22350622, 2012).
lung adenocarcinoma (3 papers, 2016 to 2023). A carcinoma that arises from the lung and is characterized by the presence of malignant glandular epithelial cells. "Moreover, Zhu H and his colleagues constructed a prognostic signature containing SPTBN1, and also found that SPTBN1 might be a potential tumor suppressor gene and could serve as an independent biomarker for predicting prognosis of patients with lung adenocarcinoma (LUAD)." (PMID 37013511, 2023). "Therefore, c-Met overexpression, HER-2 gene amplification, and SPTBN1-ALK gene fusion can coexist in lung adenocarcinoma and may become a potential biomarker of cancer refractory to crizotinib, chemotherapy, and radiotherapy as well as of a relatively poor prognosis." (PMID 27496196, 2016).
Obesity (3 papers, 2015 to 2025). Accumulation of substantial excess body fat. "Elevated levels of SPTBN1 and Caspase-3 have been observed in both obese humans and mice, linking SPTBN1 to obesity pathogenesis." (PMID 40301996, 2025). "Targeting βII-Spectrin (SPTBN1) in a tissue-specific manner offers a promising avenue for managing obesity and its complications, including progression to liver diseases and HCC." (PMID 40301996, 2025). "HFD and Western diet (WD) induce Caspase-3-mediated cleavage of SPTBN1, and the resulting fragments translocate to the nucleus, driving the expression of pro-obesity genes." (PMID 40301996, 2025). "Liver-specific knockout of SPTBN1 in mice protects against obesity, providing a potential therapeutic avenue for metabolic disorders." (PMID 40301996, 2025). "This leads to multiple future therapeutically relevant opportunities: Obesity Treatment: Modulating SPTBN1 expression or function could provide a novel therapeutic strategy to combat obesity by inhibiting the Caspase-3–SPTBN1 axis and its downstream effects." (PMID 40301996, 2025). "Therapeutic strategies targeting Caspase-3 cleavage of SPTBN1 or modulating nuclear translocation of SPTBN1 cleavage products could mitigate obesity-related metabolic dysregulation." (PMID 40301996, 2025). "We observed altered microbial populations in an obesity-induced mouse model of cancer, where ammonia promotes caspase-3-mediated cleavage of the SMAD3 adaptor βII-spectrin (SPTBN1)." (PMID 40311681, 2025).
asthma (2 papers, 2024 to 2026). "Differentially methylated loci were near genes related to asthma (ITPR2, MAPK1), lung function (FKBP11), mitochondrial function (MRPL20, SPTBN1), inflammation (C3), and immune function (N4BP3, EIF5)." (PMID 41749276, 2026). "The 15 most significant DEGs included genes known to play a role in wound healing (FN1, CDH11), immune response (VSIG4, HS3ST4), and asthma drug response (PTHHD4, SPTBN1, FKBP5)." (PMID 38806494, 2024).
colon cancer (2 papers, 2023 to 2025). "To define a clear role of SPTBN1-cleaved fragments in ammonia toxicity, we overexpressed N-SPTBN1 in human colon cancer cells (SW480), followed by treatment with ammonia (NH4Cl) and TGF-β." (PMID 40311681, 2025). "We first observed that ammonia activates caspase-3 in a dose-dependent manner in HCT116 human colon cancer cells, leading to an increase in SPTBN1-cleaved fragments, with the highest cleavage observed at 10 mM NH4Cl." (PMID 40311681, 2025). "We also find that SPTBN1 interacts with CEACAM1 cytoplasmic domain in colon cancer cells." (PMID 40311681, 2025). "Next, we performed RNA-sequencing analyses on SW480 human colon cancer cells treated with ammonia and TGF-β following SPTBN1 knockdown." (PMID 40311681, 2025). "Therefore, we investigated the role of SPTBN1-cleaved fragments in ammonia-mediated alterations in TGF-β–SMAD3 signaling, utilizing siRNA targeting SPTBN1 (siSPTBN1) in SW480 and Caco-2 human colon cancer cells and treated cells with ammonia." (PMID 40311681, 2025).
fatty liver disease (2 papers, 2022 to 2024). A reversible condition wherein large vacuoles of triglyceride fat accumulate in liver cells via the process of steatosis. "We observed that similar to the human fatty liver disease, our obese mice show marked sarcopenia that is corrected in the liver-specific knockout of SPTBN1." (PMID 38323119, 2024). "We also observed that, similar to human fatty liver disease, obese mice show marked sarcopenia with increased Myostatin levels that are corrected in the liver-specific knockout of SPTBN1." (PMID 38323119, 2024). "A previous study showed that SIRT6 interacted with spectrin beta chain, non-erythrocytic 1 (SPTBN1) to crosstalk with TGF-β signaling, and contributed to fatty liver disease." (PMID 36558977, 2022).
hearing loss (2 papers, 2019 to 2022). "LMO7 colocalizes with eQTLs for the gene in GTEx skeletal muscle and SPTBN1 in thyroid tissue, such that decreased expression of these genes is correlated with increased risk for hearing loss in humans." (PMID 35661827, 2022). "This study is the largest GWAS meta-analysis of ARHI to date and identified 7 associated loci, of which 5 are novel (FXYD5, IPP, SPIRE2, SPTBN1 and TRIL) and 2 have been previously related to hearing loss (ILDR1, ISG20)." (PMID 31645637, 2019).
leiomyoma (2 papers, 2021 to 2022). A well-circumscribed benign smooth muscle neoplasm characterized by the presence of spindle cells with cigar-shaped nuclei, interlacing fascicles, and a whorled pattern. "Our data showed downregulation of SPTBN1 in leiomyomas; reduced expression of SPTBN1 correlated with shorter survival of patients with cancer." (PMID 35641855, 2022).
schizophrenia (2 papers, 2012 to 2022). A major psychotic disorder characterized by abnormalities in the perception or expression of reality. "It was reported that SPTBN1 interacted with calmodulin in a calcium-dependent manner, which was believed to have close link with the pathophysiological process of schizophrenia." (PMID 35484098, 2022).
seminoma (2 papers, 2023 to 2025). A radiosensitive malignant germ cell tumor found in the testis (especially undescended), and extragonadal sites (anterior mediastinum and pineal gland). "A Western blot of total cell lysates revealed comparable SPTBN1 levels between the three seminoma cell lines." (PMID 38069214, 2023). "Our analysis of SPTBN1 mRNA levels in non-seminoma (N-S; N = 65) and seminoma (S; N = 68) TGCT specimens revealed significantly lower levels of SPTBN1 mRNA in seminoma samples compared to non-seminomas." (PMID 38069214, 2023). "Regardless, the significance of our research lies in the identification of SPTBN1 as a factor that is able to impair the nuclear oncogenic activity of PTTG1 in seminoma." (PMID 38069214, 2023). "In order to translate these results to clinical practice, we verified the interplay between PTTG1 and SPTBN1 in human seminoma specimens from patients who underwent therapeutic orchiectomy." (PMID 38069214, 2023). "The Atlas database revealed that seminomas that contained higher nuclear PTTG1 levels showed significantly lower SPTBN1 levels in comparison to non-seminomas." (PMID 38069214, 2023). "The new findings of our research suggest that in human seminoma, SPTBN1 plays a key role as a cytoplasmic constraint for PTTG1, impairing its nuclear oncogenic activity." (PMID 38069214, 2023). "The Atlas database interrogation revealed that in human seminoma specimens, SPTBN1 levels were significantly lower in comparison to non-seminoma testicular tumors." (PMID 38069214, 2023). "Further studies in human seminoma tissues are needed to correlate the interplay of PTTG1/SPTBN1 with tumor staging in order to provide a translational impact for our data." (PMID 38069214, 2023). "Interestingly, SPTBN1 regulates the cytoplasmic constraint of pituitary tumor-transforming gene 1, promoting the invasive capability of human seminoma." (PMID 40321316, 2025). "According to our model, the interaction between PTTG1 and SPTBN1 could be impaired during seminoma development, leading to a progressive PTTG1 nuclear localization." (PMID 38069214, 2023). "This PTTG1/SPTBN1 interaction could be negatively affected during seminoma tumor invasion, and we reported a progressive PTTG1 nuclear localization in this setting." (PMID 38069214, 2023). "We therefore wondered if SPTBN1 could act as a cytoplasmic scaffold of PTTG1 in seminoma and be one the factors responsible for its subcellular localization." (PMID 38069214, 2023). "Furthermore, we analyzed the colocalization of PTTG1/SPTBN1 in human specimens from patients who underwent therapeutic orchiectomy for seminomas." (PMID 38069214, 2023). "To this aim, we evaluated the subcellular distribution of these proteins through confocal microscopy, and ex vivo, we confirmed that the colocalization of PTTG1/SPTBN1 occurs to a significantly higher extent in the area of the seminoma showing greater cytoplasmic PTTG1 levels." (PMID 38069214, 2023). "During seminoma progression, SPTBN1 downregulation could occur, as reported for different cancer histotypes." (PMID 38069214, 2023). "Moreover, we demonstrated that this phenomenon has a functional impact on seminoma tumor progression; indeed, in the 3D sphere-forming assay, we found that the downregulation of SPTBN1 led to an increase in the diameter of TCAM2 spheres, which was induced by PTTG1 nuclear translocation." (PMID 38069214, 2023). "This prompted us to investigate the functional interplay between SPTBN1 and PTTG1 in seminoma tumors." (PMID 38069214, 2023). "Overall, these results suggest that SPTBN1, along with PTTG1, is a potential prognostic factor useful in the clinical management of seminoma." (PMID 38069214, 2023). "Of note, in our seminoma cellular models, we found that PTTG1 and SPTBN1 interact almost exclusively in TCAM2 cells in which PTTG1 is more cytoplasmic in comparison to the other cell lines." (PMID 38069214, 2023).
seminoma (continued). "In human seminoma specimens, we found a strong PTTG1/SPTBN1 colocalization that decreases in areas with nuclear PTTG1 distribution." (PMID 38069214, 2023). "Therefore, this would emphasize the eligibility of SPTBN1 as a novel prognostic factor, along with PTTG1, for the clinical management of seminoma tumors." (PMID 38069214, 2023).
Aphasia (1 paper, 2026). An acquired language impairment of some or all of the abilities to produce or comprehend speech and to read or write. "In addition, pathogenic variants in SPTBN1 have been associated with aphasia." (PMID 40836029, 2026).
apraxia (1 paper, 2026). Apraxia is a neurological disorder characterized by the inability to perform tasks or movements, despite having the desire and physical ability to perform them. "Interestingly, a likely pathogenic missense variant in SPTBN1 has been described in a proband with speech delay, and a missense variant of unknown significance in TRIO in a proband with childhood apraxia of speech." (PMID 40836029, 2026).
chronic myeloid leukemia (1 paper, 2015). "SPTBN1 gene fusions have been reported in atypical myeloproliferative disorders (MPDs) and atypical chronic myeloid leukemia." (PMID 26678488, 2015).
developmental and epileptic encephalopathy (1 paper, 2022). An epilepsy associated with developmental impairment that may be due to either the underlying etiology or the superimposed epileptic activity, or both. "Mendelian disease-gene links are increasingly being recognized for the spectrin genes, with SPTAN1, SPTBN1, SPTBN2 and SPTBN4 linked to neurological diseases such as developmental and epileptic encephalopathy (DEE), ataxia, hereditary spastic paraplegia, and hereditary motor neuropathy." (PMID 36238261, 2022).
Dystonia (1 paper, 2025). An abnormally increased muscular tone that causes fixed abnormal postures. "No carriers of presumably pathogenic variants in other dystonia candidate genes were detected among our 1924 patients, including the recently proposed genes ATP5F1B, ACBD6, and SPTBN1." (PMID 40533913, 2025). "Screening our data for proposed dystonia candidate genes identified presumably pathogenic variants in CHD6, KCNN2, KLC1, NR4A2, and ZMYND11, but not in others, for example, ATP5F1B, ACBD6, CIZ1, SHQ1, and SPTBN1." (PMID 40533913, 2025).
hemorrhage (1 paper, 2024). Loss of blood from the vascular compartment to the exterior or into nonvascular body space as a result of rupture or severance of the blood vessels. "Plaque SPTBN1 mRNA and protein expression were found to correlate with an enhanced presence of intraplaque hemorrhage and future cardiovascular disease (CVD) events during follow-up." (PMID 38780883, 2024).
Hypertension (1 paper, 2019). The presence of chronic increased pressure in the systemic arterial system. "Our search revealed both known KDs showing connections to hypertension or relevant conditions in one or more types of studies (99 KDs; such as GNAS, SLC2A3, IRS1, ADM, and SERPINE1) and relatively novel KDs in BP studies (such as SPTBN1 and GNB1)." (PMID 30931314, 2019).